SDC1 (syndecan 1)
Diseases named in the same sentence as SDC1 in open-access papers (continued):
Sharing a sentence is not in itself a finding about the gene and the disease.
tumor (continued). "Accumulating evidence suggests that syndecan-1 is involved in the stimulation of cancer stem cells or tumor-initiating cells, and this may affect disease relapse and resistance to chemotherapy." (PMID 32983743, 2020). "High stromal syndecan-1 expression was found to enhance the proliferation of BC cells as well as to facilitate angiogenesis, being partly responsible for the higher mammographic density of tumor tissues." (PMID 32847060, 2020). "Overexpression of Wnt1 failed to trigger the accumulation of mammary CSCs and progenitors for oncogenic transformation in syndecan-1-null mice, whereas an enrichment in the progenitor population and tumor initiation were induced in syndecan-1 expressing counterparts." (PMID 33330458, 2020). "Therefore, we examined the membranous and cytoplasmatic SDC1 intensity of tumor cells, as well as that of stromal cells separately." (PMID 33114033, 2020). "Although syndecan-1 may be important for tumorigenesis in certain tumor types, patterns of HSPG expression in CSC populations appear to be contextual and tissue-specific." (PMID 33330458, 2020). "An excess of growth factors, bound by heparan sulfate chains of syndecan-1, abnormally expressed on the surface of stromal cells may lead to aggressive clinical tumor phenotype." (PMID 32388727, 2020). "Taken together, these results underline both the advantage of MSOT imaging in relation to NIRF imaging, i.e., deeper imaging depth as well as the great potential of this syndecan-1 tracer for combined MSOT/NIR imaging of a wide arrange of tumors, given the broad tumor expression of syndecan-1." (PMID 33371487, 2020). "Furthermore, it was suggested that tumor SDC-1 downregulation facilitates ex vivo polarization of CD4+ Th17 and Treg cells of non-inflammatory BC, possibly through increased expression of IL-23 and DLL4." (PMID 32847060, 2020). "In accordance with previously published results in chemo-naïve patients, the correlation between high stromal SDC1 expression and higher tumor-specific mortality was also described in patients with oral squamous carcinoma who received neoadjuvant cisplatin-containing chemotherapy." (PMID 33114033, 2020). "SDC1 also promotes tumor growth, angiogenesis, and invasive phenotype in many tumor models." (PMID 32756007, 2020). "Similarly, in gastric carcinomas, high Sdc-1 expression correlated with a less aggressive tumor phenotype." (PMID 33330449, 2020). "In addition to plasma cells, membranous and cytoplasmatic SDC1 staining were characteristic for tumor cells." (PMID 33114033, 2020). "Indeed, in MDA-MB-231 BC xenografts, the presence of fibroblasts enhanced tumor growth, which was further facilitated by the overexpression of syndecan-1." (PMID 32847060, 2020). "SDC1 concentrations were evaluated by ELISA in 52 baseline and 90 follow-up serum samples and tissue expressions were analyzed by immunohistochemistry in an independent cohort of 69 formalin-fixed paraffin-embedded tumor samples." (PMID 33114033, 2020). "It should be mentioned that the outcome of syndecan-1 activity on tumor progression could be contextual." (PMID 32796709, 2020). "Importantly, the expression of syndecan-1 to stroma was correlated with both tumor growth and vessel density in BC patient biopsies." (PMID 32847060, 2020). "A positive correlation between SDC1 and B-FN was found when these two proteins were dosed simultaneously in ascites from 45 patients (Pearson’s correlation, r = 0.3512, p = 0.0180), indicating an involvement of these two molecules in tumor progression." (PMID 31443604, 2019). "Moreover, we demonstrate that tumor Sdc-1 silencing enhances the polarization of Th cells under indirect conditions towards Th1 and under both co-culture conditions towards Th17, and Treg subsets, but not towards Th2 subset in non-IBC." (PMID 31145753, 2019).
tumor (continued). "Preclinical and clinical studies have suggested that metastatic cancers can be at least partly alleviated by targeting the heparanase/syndecan-1 axis or syndecan heparan sulfate proteoglycans, which are involved in the formation of exosomes and tumor cell dissemination." (PMID 30925925, 2019). "It is possible that the mechanism of syndecan-1/heparan sulfate modulation in the tumor cell microenvironment could be mediated by exosomes." (PMID 30922347, 2019). "Overall, this study indicates a low frequency of the circulating antitumor Th1 subset in IBC and suggests that tumor Syndecan-1 silencing enhances ex vivo polarization of CD4+ Th17 and Treg cells of non-IBC, whereby Th17 polarization is possibly mediated via upregulation of IL-23 and DLL4." (PMID 31145753, 2019). "Using in vitro assays of osteoclastogenesis and bone resorption, it was shown that enhanced osteoclastogenesis also requires the presence of syndecan-1, a proteoglycan whose shedding from tumor cell surfaces is enhanced by the expression of heparanase and protein agents, such as IL-8." (PMID 31847214, 2019). "These cells were used to explore the impact of tumor Sdc-1 silencing on polarization of CD4+ T cells isolated from non-IBC (under direct and indirect co-culture conditions) and IBC patients (under indirect co-culture conditions) towards Th1, Th2, Th17 and Treg subsets." (PMID 31145753, 2019). "Moreover, we describe a prominent role of SDC1 in VM, since targeting of this proteoglycan was able to inhibit the formation of tubule-like structures by tumor cells, both in vitro and in vivo." (PMID 31443604, 2019). "To gain information on the possible tumor origin of SDC1, we tested 31 plasma and ascites pairs." (PMID 31443604, 2019). "Moreover, ATPP-mediated sensitization of tumor cells expressing the cell surface proteoglycan CD138 (Syndecan-1) showed similar efficacy, highlighting the transferability of the ATPP approach to other cancer targets." (PMID 31555260, 2019). "It turned out that the highest SDC1 serum levels exist in metastatic BCs, which supported the hypothesis that the circulating SDC1 ectodomain exerts tumor-promoting effects on distant metastatic sites." (PMID 30135409, 2018). "Syndecan-1 has been reported to play important roles in tumor growth." (PMID 30135409, 2018). "Evidence suggests that syndecan-1 induced tumor growth may be attributed to its promotion of cancer cell proliferation." (PMID 30135409, 2018). "We propose that SDC-1 repression by ZEB1 occurs mainly in epithelial cells without oncogene or tumor suppressor mutations." (PMID 30065348, 2018). "Based on these notions, we next investigated whether the increased tumor size in Sdc1-KO mice is due to an exacerbated chronic inflammation in their colons." (PMID 28350804, 2017). "We also determined the effects of SDC1 knockdown on tumor growth in vivo using a xenograft model." (PMID 28422726, 2017). "Importantly, a macroscopically apparent and statistically significant (p = 0.042) increase in tumor burden was easily detected in Sdc1-KO mice as compared to wt animals." (PMID 28350804, 2017). "The heparan sulfate proteoglycan Syndecan-1 acts as a coreceptor for growth factors and chemokines, modulating inflammation, tumor progression, and cancer stemness, thus it may emerge as a molecular marker for IBC." (PMID 28270211, 2017). "Focusing on one of the most aggressive CTC type, which from the primitive tumor spreads to the CNS, we documented that CSF floating cancer cells overexpress syndecan-1, MUC-1 and, in a proportion of cases, the putative stem-cell markers CD15, CD24, CD44, and CD133 in BCLM." (PMID 28399903, 2017). "Moreover, YKL-40 was likely to promote tumor angiogenesis by interacting with syndecan-1 on endothelial cells as well as metastasis by stimulating production of pro-inflammatory and pro-invasive factors such as MMP-9, CCL2 and CXCL2." (PMID 28036271, 2017).
tumor (continued). "Also, syndecan-1 altered expression can affect tumour cells via junB-FLIP long signals, involving apoptosis resistance and increased proliferation." (PMID 29207682, 2017). "Moreover, syndecan-1 cCTF (cytoplasmic C-terminal fragment) antagonizes syndecan-1 dependent tumor cell migration by competing with the full length syndecan-1 for intracellular interaction partners and thereby reduces signaling of syndecan-1." (PMID 27834933, 2016). "This suggests that a combined action of invasive cancer cells' secreted factors with the effect of irradiation-mediated senescence on the overexpression of SDC1 may promote even further tumor progression." (PMID 27434331, 2016). "Accordingly, it seems that senescent cells may add one more alteration (i.e. increased SDC1 expression) in the microenvironment in favor of tumor growth." (PMID 27434331, 2016). "We have previously reported that while SDC1 is not always elevated in BCa urine samples relative to controls it can provide prognostic information based on its association with tumor grade and stage." (PMID 26830497, 2016). "Furthermore, we investigated the characteristics of the senescent cells, with an emphasis on the expression of SDC1, given that its expression in the stroma can create a favorable environment for tumor cell growth." (PMID 27434331, 2016). "In summary, we have demonstrated a regulatory effect of Sdc1 on the tumor ECM architecture." (PMID 26909794, 2016). "To better understand the role of integrin αvβ3 in the generation of ECMs with tumor promoting properties, we tested whether the forced activation of αvβ3 would bypass the requirement for Sdc1." (PMID 26909794, 2016). "Consequently cell-membrane bound, stromal, and soluble shed syndecan-1 seem to carry different, highly tissue specific information for individual tumor types that has to be viewed as contributing parts of a whole spectrum." (PMID 26420915, 2015). "All these syndecan-1 mediated responses are known to drive tumor cell migration." (PMID 26378057, 2015). "Thus, in our experimental setup the syndecan-1 cCTF critically influences proadhesive signaling events, which are syndecan-1 dependent and required for tumor cell migration." (PMID 26378057, 2015). "Therefore, we established an immunocompetent MM mouse model, where the tumor is induced by injection of the 5T33 MM cell line, which expresses the CD138 antigen (syndecan-1), a hallmark of all MM cells, and ovalbumin (OVA)." (PMID 26098691, 2015). "However, based on the data to date, it is difficult to directly correlate the levels of SDC1 expression with tumor characteristics and prognostic significance for all cancers in general and formulate personalized clinical treatment approaches." (PMID 26293675, 2015). "We here demonstrate that γ-secretase mediated cleavage generates a cytoplasmic syndecan-1 fragment (cCTF) and we ask whether this fragment can still exert specific functions that may be relevant in the context of tumor cell migration." (PMID 26378057, 2015). "In the serum of larynx and hypopharynx carcinoma patients the soluble syndecan-1 levels decrease after surgery and/or radiotherapy and the levels may increase at the time of tumor recurrence." (PMID 26420915, 2015). "Syndecan-1 present in the stromal component of different malignant tumors generally indicates poor prognosis through promotion of tumor cell invasion and development of metastasis and it also might stimulate the growth of epithelial cells." (PMID 26420915, 2015). "SDC1 acts to potentiate the signaling of cancerous and stromal cells in the tumor microenvironment." (PMID 26293675, 2015). "High serum levels of syndecan-1 were observed in patients with lung epithelial tumors of poor prognosis suggesting that syndecan-1 may represent a versatile tumor marker." (PMID 26378057, 2015). "Moreover, there exist several mechanisms by which syndecan-1 can potentially influence tumor growth and spread." (PMID 26378057, 2015).
tumor (continued). "Tumor formation is suppressed when cells lack endogenous syndecan-1." (PMID 26378057, 2015). "More specifically, enhanced expression of SDC2 in the tumour stroma significantly correlates with overall survival and is indicative of lymphonodal metastasis, whereas aberrant increased of SDC1 transcription is indicative of the presence of distant metastases." (PMID 25935541, 2015). "The expression of cell surface syndecan-1 in tumor tissue is context-specific." (PMID 26420915, 2015). "Experimental overexpression of full length syndecan-1 enhances cell-ECM cohesion and restricts cell migration, whereas the loss of the syndecan-1 ectodomain from the cell surface increases the migratory capacity of tumor cells." (PMID 26420915, 2015). "Since syndecan-1 regulates tumor cell migration we questioned whether its proliferative and promigratory function is influenced by the accumulation of syndecan-1 cCTF, which can originate from proteolysis by γ-secretase." (PMID 26378057, 2015). "SDC-1 down regulation potentially generates the ability to form a dedifferentiated invasive or migrating tumour cell, mobilization of growth factors from epithelial tumour cell surfaces and ECM and soluble factors needed for the establishment of the cancer-associated non-malignant stroma 97,98." (PMID 25598217, 2015). "This is indicated by several reports showing that syndecan-1 contributes to tumor growth in vivo." (PMID 26378057, 2015). "Both nuclear syndecan-1 and HS chains inhibit nuclear histone acetyl-transferase activity and acetylation of histones thereby decreasing gene expression that drive tumor progression." (PMID 26420915, 2015). "Interestingly, most studies have shown distinct cellular expression patterns for SDC1, in which membranous and cytoplasmic expression profiles were different in tumor samples compared to control samples from different types of cancers." (PMID 26293675, 2015). "By these pathways syndecan-1 is thought to contribute to tumor cell migration." (PMID 26378057, 2015). "As a consequence, shed SDC-1 mediates the signaling of bound growth factors leading to a strong downstream signaling to host cells, triggering the microenvironment to support aggressive tumor growth." (PMID 24551591, 2014). "However, it is noteworthy that, depending on tumour type, syndecan-1 has shown to be either a tumour suppressor or a tumour promoter." (PMID 25147801, 2014). "In addition, both heparanase and SDC-1 are retained as cargo within exosomes and subsequently influence not only the behavior of the tumor microenvironment within the tumor niche and distant sites, but also the growth of the metastasizing cells." (PMID 24551591, 2014). "In addition, VEGF expression is significantly upregulated in cells expressing high levels of heparanase, leading to decreased nuclear SDC-1 and an aggressive tumor phenotype." (PMID 24551591, 2014). "If less membrane bound SDC-1 is present in a tumor mass, then it might be expected that less shed or released SDC-1 would be present in the soluble fraction of voided urine from patients with more aggressive or advanced BCa." (PMID 24524203, 2014). "In a number of malignancies, the expression of SDC-1 correlates with tumor stage and grade, but the association between SDC-1 status and BCa has not been extensively studied." (PMID 24524203, 2014). "This dual effect of syndecan-1 seems to depend on the source and forms of syndecan-1: whether it is tumour cell-derived or synthesized by the stroma and whether it is cell surface-bound or shed." (PMID 25147801, 2014). "Furthermore, fibroblast growth factor receptor 2 (FGFR2); ARHGEF4, which acts as a guanine nucleotide exchange factor; and SDC1, a member of the syndecan proteoglycan family, were also expressed at significantly lower levels in ulcerated tumours." (PMID 23383013, 2013).
tumor (continued). "The shed syndecan-1 can act opposing compared to cell-surface syndecan-1, since potentially it is able to sequester the GFs and other HS-binding soluble factors from the microenvironment of the tumor cell." (PMID 24392351, 2013). "Changes in syndecan-1 level can have remarkable consequences for tumor cell behavior." (PMID 24392351, 2013). "Our study suggests that effects on tumor cells through stimulation of TLRs by endogenous ligands such as soluble syndecan-1, matrix metalloproteinase products, heat-shock proteins, HMGB-1, which are released due to cell necrosis, should also be considered in MM." (PMID 23593278, 2013). "We used two different antibodies to detect different domains of SDC1 in the tumor cells." (PMID 24373193, 2013). "Thus, syndecan-1 seems to have antithetic roles in different cancer types having inhibitory role on tumor formation and progression in many different epithelial malignancies but also promoting the growth of others." (PMID 24392351, 2013). "OPN may down-regulate the expression of Syndecan-1 to reduce the adhesion between tumor cells, and thereby encouraging tumor metastasis." (PMID 22537906, 2012). "In vivo, both full length and truncated syndecan-1 increased tumour growth and metastatic rate." (PMID 22745764, 2012). "Syndecan-1 is overexpressed in some tumor types, whereas suppressed in others." (PMID 23144729, 2012). "However, accumulating evidence suggest that syndecan-1 influences tumor growth and proliferation in a complex and tumor type specific manner." (PMID 23144729, 2012). "Our study demonstrates that syndecan-1 plays an important role in mesenchymal tumor behavior." (PMID 21731601, 2011). "The performed bioassays show that the overexpression of syndecan-1 may influence mesenchymal tumor cell adhesion, and decrease the tumor cell motility and migration." (PMID 21731601, 2011). "In the present study, we aimed to investigate the role of syndecan-1 in tumor cell adhesion and migration, with special focus on the importance of its distinct protein domains, to better understand the structure-function relationship of syndecan-1 in tumor progression." (PMID 21731601, 2011). "Heparanase is known to promote progression in a number of cancers and its presence may be a major determinant on whether SDC-1 plays a tumor-promoting or tumor inhibitory role." (PMID 21655218, 2011). "Further, we studied whether overexpression of syndecan-1 may affect the basal and chemoattractant-induced mesenchymal tumor cell migration." (PMID 21731601, 2011). "One direction that may help to unravel its role in cancer is to examine the regulation of SDC-1 by tumor suppressive or promoting agents." (PMID 21655218, 2011). "The finding that syndecan-1 shed from the surface of tumor cells is another important mediator of osteoclastogenesis identifies the heparanase–syndecan-1–cytokine axis as a novel target for inhibiting osteoclastogenesis and ultimately for preventing the consequences of bone metastases." (PMID 20200931, 2010). "In addition, in vitro osteoclastogenesis assays demonstrated that shed syndecan-1 was required for the enhanced osteoclastogenic activity of the tumor cells." (PMID 20200931, 2010). "This ability of heparanase to regulate nuclear syndecan-1 may represent a mechanism whereby heparanase influences gene transcription with downstream effects that promote the aggressive tumor phenotype." (PMID 19305494, 2009). "Only in 17 cases did more than 75% of the tumor cells stain for syndecan-1." (PMID 18590537, 2008). "Generally, higher levels of syndecan-1 immunostaining were observed in the well-differentiated tumours, whereas significant reduction of syndecan-1 immunostaining was observed in poorly differentiated tumours." (PMID 18542065, 2008).